H19 (H19 imprinted maternally expressed transcript)
Diseases named in the same sentence as H19 in open-access papers (continued):
Sharing a sentence is not in itself a finding about the gene and the disease.
colorectal cancer (continued). "The overall biological role and clinical significance of long non-coding RNA H19 in colorectal cancer (CRC) remain largely unknown." (PMID 26989025, 2016). "One study has indicated that lncRNA H19 generates miR-675 in colorectal cancer." (PMID 27270317, 2016). "Finally, H19 was significantly upregulated in colorectal cancer patient tissues, indicating the pathological importance of H19 in tumor progression." (PMID 26068968, 2015). "Furthermore, H19 is the precursor of miR-675, which downregulates the tumor suppressor retinoblastoma in human colorectal cancer." (PMID 23887658, 2013). "Although the precise mechanism of LOI of H19 on gene expression remains to be proven, it was confirmed that LOI of H19 is an organ-specific genetic change and that H19 overexpression may play an important role in the progression of esophageal and colorectal cancers." (PMID 35674441, 2022). "Besides, several studies showed that H19 was upregulated in metastatic cancer tissues and could promote cancer metastasis, including colorectal cancer." (PMID 33267897, 2020). "Likewise, we have found H19 to be most strongly associated with the EMT gene set, in agreement with recent work describing the mechanism by which H19 promotes EMT in colorectal cancer through miRNA sequestration." (PMID 29963224, 2018). "Recently H19 expression has been previously reported to be up-regulated in many cancers including hepatocellular carcinoma, ovarian cancer, bladder cancer, breast cancer, testicular cancer, choriocarcinoma, colorectal cancer, esophageal cancer, glioma, gastric cancer and lung cancer." (PMID 27120794, 2016). "However, to our knowledge, no data previously has explored the correlation between H19 genetic variants and colorectal cancer susceptibility in a Chinese population." (PMID 27027436, 2016). "However, the association between genetic variants in H19 and colorectal cancer susceptibility has not been reported." (PMID 27027436, 2016). "In addition, lncRNA H19 inhibits RB in human colorectal cancers." (PMID 26461935, 2015). "In colorectal cancer, exosomal lncRNAs like CCAL and H19, which are produced by CAFs, also play a significant role in modulating the tumor microenvironment." (PMID 40781643, 2025). "In the context of colorectal cancer, CAF-derived H19 also engages in a competitive binding mechanism with β-catenin to miR-141, leading to the upregulation of β-catenin and the subsequent activation of the pathway." (PMID 39717771, 2024). "LncRNAs like H19, FAL1, and CCAL, encapsulated in CAF-derived EVs, can induce oxaliplatin resistance in colorectal cancer cells upon internalization." (PMID 39717771, 2024). "Thus, H19 could be a promising therapeutic target for the treatment of colorectal cancer." (PMID 39830506, 2024). "Increased expression of H19 was correlated with tumor differentiation, TNM staging, and unfavorable prognosis in colorectal cancer." (PMID 39830506, 2024). "LncRNA H19, as a oncofetal transcript, has been shown to promote SIRT1-mediated autophagy in colorectal cancer (CRC) cells, which in turn confers resistance to 5-fluorouracil." (PMID 36901813, 2023). "Moreover, the H19-miR-194 axis is also involved in the epithelial-mesenchymal transition of colorectal adenocarcinoma, gallbladder cancer cell proliferation, 5-Fu resistance in colorectal cancer, suggesting that the H19-miR-194 axis is essential in tumor development." (PMID 37253635, 2023). "Curiously, resistance to oxaliplatin treatment is transferred by H19 contained in exosomes to sensitive cells by OXA-resistant cells both in vivo and in vitro colorectal carcinoma." (PMID 35955440, 2022). "In existing studies, lncRNA H19 has been reported to upregulate WNT signaling activity by regulating miR-29b, thus promoting the EMT of colorectal cancer cells." (PMID 34178988, 2021).
colorectal cancer (continued). "Moreover, lncRNA H19 could also up-regulate cancer-related mRNA expressions by functioning as a ceRNA to influence phosphatidylinositol-3-kinase (PI3K)/Akt signaling pathway, and lncRNA H19 is associated with poor prognosis in colorectal cancer." (PMID 33028275, 2020). "High H19 expression rates are found in patient samples at different tumor node metastasis (TNM) stages, and correlated with chemoresistance of colorectal cancer cells in vitro and in vivo after treatment with oxaliplatin." (PMID 33291403, 2020). "To further investigate the role of hnRNPA2B1 in H19-regulated metastasis in colorectal cancer, we separated the nuclear fractionation and cytoplasm fractionation of HCT116 and SW480 cells to investigate the distribution of H19 in subcellular fraction." (PMID 32698890, 2020). "H19 facilitates the EMT by sponging MiR-138 and MiR-200a to promote ZEB1 and ZEB2 in colorectal cancer." (PMID 33193379, 2020). "Our study discovers the critical role of H19 in mediating the pro-metastatic potential of CRC and highlight the potential of H19 acting as a prognostic predictor and therapeutic target for colorectal cancer." (PMID 32698890, 2020). "By directly binding to hnRNPA2B1, H19 activates Raf-ERK signaling, resulting in the induction of EMT, and eventually promotes migration, invasion and metastasis of colorectal cancer cells." (PMID 32698890, 2020). "H19 regulates PI3K–Akt signal pathway through a competing endogenous RNA network and predicts poor prognosis in colorectal cancer." (PMID 31164794, 2019). "LncRNA H19, located on chromosome 11 in humans, contributes to EMT formation by regulating relevant signaling pathways or molecules in colorectal cancer, lung cancer, breast cancer, and pancreatic cancer." (PMID 31744051, 2019). "Excessive H19 functioned as a “molecular sponge” to absorb miR-200a and miR-138, and promoted EMT of colorectal cancer cell lines." (PMID 28230721, 2017). "Another fascinating finding suggests that H19 promotes EMT by sponging two EMT repressors, miR-134 and miR-200 in colorectal cancer metastasis." (PMID 26536864, 2015). "miR-675 is processed from the first exon of H19 and functionally downregulates the tumor suppressor gene retinoblastoma (RB1) in human colorectal cancer, further implying an oncogenic role for H19." (PMID 21489289, 2011). "For instance, in glioblastoma tumorigenesis, HDAC2 knockdown has been shown to impede tumor-sphere formation and proliferation by upregulating miR-3189-mediated GLUT335.In contrast, HDAC2 functions as a metastasis suppressor in colorectal cancer by impeding EMT and the expression of H19 and MMP1436." (PMID 37495623, 2023). "Taken together, these results suggested that H19 promoted colorectal cancer metastases in vitro and in vivo, but exerted no influence on cell viability." (PMID 32698890, 2020). "The lncRNA H19 has been reported to function as a ceRNA for miR-138 and miR-200a to suppress the target gene expressions of Vimentin, ZEB1, and ZEB2, thereafter to promote epithelial to mesenchymal transition in colorectal cancer." (PMID 33028275, 2020). "H19 may promote EMT by sponging miRNA-138 and miR-200a, and then upregulation of their downstream targets Vimentin,ZEB1 and ZEB2 in colorectal cancer." (PMID 33267897, 2020). "The result displayed that SNAI1 (Snail), a crucial EMT transcript factor, was one of the most relevant genes with H19, suggested H19 may involve in the progression of EMT in colorectal cancer." (PMID 32698890, 2020). "Nevertheless, the molecular mechanism of H19 to upregulate the metastatic capability of tumor cells in colorectal cancer were not clear." (PMID 32698890, 2020). "For example, lncRNA H19 could activate the Wnt/β-catenin pathway to mediate the epithelial to mesenchymal transition (EMT) and migration in colorectal cancer." (PMID 32714183, 2020).
colorectal cancer (continued). "Additionally, lncRNA H19 identified as an independent prognostic factor of CRC patient survival, regulates essential Rb-E2F and CDK8-β-catenin signaling in colorectal cancer." (PMID 29340086, 2017). "XIST, MALAT1, H19, and KCNQ1OT1 were ranked in the top four prediction list of colorectal cancer." (PMID 26278472, 2015). "Furthermore, H19, as a precursor of miR-675, may antagonize the tumor suppressor function of retinoblastoma (RB) through miR-675-mediated translational repression, which was reported to be an important mechanism involved in the pathogenesis of human colorectal cancer." (PMID 23965803, 2013). "Using a mouse model for colorectal cancer, it was shown that mice lacking H19 manifested an increased polyp count compared to wild-type." (PMID 21489289, 2011). "Additionally, H19-enriched and Wnts-enriched CAF-EVs promote chemoresistance in colorectal cancer." (PMID 36831417, 2023). "Interestingly, another study revealed that H19 might increase phosphorylation levels of components of MAP kinase pathway, such as pMEK and pERK, in colorectal cancer." (PMID 30557328, 2018).
glioma (142 papers, 2011 to 2025). A benign or malignant brain and spinal cord tumor that arises from glial cells (astrocytes, oligodendrocytes, ependymal cells). "H19 is expressed in both hepatocellular carcinoma and adult glioma-associated endothelial cells within the exosomes, which promote tumor angiogenesis." (PMID 37444408, 2023). "Mechanistic evidence suggests that lncRNA H19 regulates the biological behavior of glioma-associated endothelial cells by inhibiting miR-29a." (PMID 37602326, 2023). "Meanwhile, overexpressing H19 in U251 and LN229 cells causes temozolomide resistance, which indicates that H19 confers temozolomide resistance to glioma cells." (PMID 35782387, 2022). "LncRNA H19 encodes a 2.3-kb long transcript and is a carcinogenic lncRNA in several cancers, including glioma." (PMID 35782387, 2022). "Prognostic value: H19 overexpression in glioma tissue was associated with poor overall and progression-free survival and more advanced tumor stage." (PMID 34322395, 2021). "Knockdown of lncRNA H19 in glioma cell lines resulted in decreased tube formation assays, whereas H19 overexpression was associated with significantly increased number of branches in tube formation assays." (PMID 34200145, 2021). "LncRNA H19 was the first identified RNA regulator implicated in multiple steps of tumorigenesis and is a potential tumorigenic LncRNA for glioma." (PMID 34081618, 2021). "H19 expression associated with immune infiltration level in glioma (partial Spearman’s correlation)." (PMID 32081833, 2020). "Another group reported that overexpressed lncRNA H19 in glioma tissues was negatively linked to the glioma prognosis and that silencing H19 inhibited the growth of glioma cells by modulating miR-675." (PMID 30498093, 2019). "Mechanistic evidence revealed that H19 modulated the biological behavior of glioma-associated endothelial cells by suppressing miR-29a." (PMID 31448238, 2019). "LncRNA H19, for instance, was reported to be significantly upregulated in glioma-associated endothelial cells cultured in glioma-conditioned medium." (PMID 31448238, 2019). "Knockdown of H19 suppresses proliferation and migration of glioma-associated endothelial cells through upregulating miR-29a." (PMID 31448238, 2019). "In glioma microvessels, the overexpression of H19 induces glioma-associated endothelial cells (GECs) proliferation, migration and tube formation via increasing the expression of angiogenic factor VASH2 as a miR-29a sponge." (PMID 29458374, 2018). "Similar to XIST, H19 was also found to be highly expressed in glioma-associated endothelial cells (GECs)." (PMID 30116729, 2018). "H19, on the other hand, regulates glioma angiogenesis and the biological behavior of glioma-associated endothelial cells by inhibiting miR-29a." (PMID 29088865, 2017). "H19 is reported to be associated with some types of carcinoma, and it is overexpressed and acts as an oncogene in breast, bladder, glioma, and prostate cancers; however, it still functions as a tumor-suppressor in hepatocellular cancer." (PMID 26989025, 2016). "More recently, increased H19 levels have been found to be associated with high grade gliomas, and H19 depletion inhibits the invasion of glioma cells." (PMID 25654223, 2015). "Further, two independent glioma gene expression data sets (Rembrandt data and GSE16011 data) were employed to examine the association between H19 expression levels and glioma grade." (PMID 24466011, 2014). "LncRNA H19 is key regulator in the pathogenesis of gliomas, but the underlying mechanisms of H19-regulated tumor progression remain unknown." (PMID 34796112, 2021). "In this study, lncRNAs expression and somatic mutation profiles in low-grade glioma genome were used to identify eight novel mutant-derived genomic instability-associated lncRNAs including H19, FLG-AS1, AC091932.1, AC064875.1, AL138767.3, AC010273.2, AC131097.4 and ISX-AS1." (PMID 34081618, 2021).
glioma (continued). "Our results define p21 acting as a downstream molecule of H19 in glioma cells, and p21 could modulate radiation-caused G2/M arrest and apoptosis." (PMID 34159190, 2021). "Knockdown of H19 has been revealed to inhibit glioma-induced angiogenesis and glioma-associated endothelial cell capabilities of proliferation, migration and tube formation by decreasing the expression of angiogenic factor vasohibin 2 through upregulation of miR-29a." (PMID 31757932, 2019). "H19 is upregulated in glioma tissues and was negatively associated with patient survival time." (PMID 30116729, 2018). "To date, the underlying role and mechanisms by which H19 may affect glioma development and in GSCs remain unclear." (PMID 26230711, 2015). "H19 was associated with tumor grade, and H19 repression inhibited glioma cell invasion." (PMID 24466011, 2014). "Significant H19 overexpression in microvessels from glioma specimens vs. normal brain microvessels leads to enhanced proliferation, migration, and tube formation with major tubule length and number of branches in H19 overexpressed glioma-associated endothelial cells." (PMID 31404273, 2019). "But the underlying role and mechanism of H19 involved in glioma development remains unclear." (PMID 24466011, 2014). "This confirmed the expression of MiR17hg, SNHG6, H19 and Pvt1 in glioma-infiltrating immune cells, consistent with our murine models." (PMID 40527978, 2025). "For example, high-grade gliomas display elevated H19 levels, whereas siRNA-mediated knockdown of H19 suppresses glioma-cell invasion." (PMID 40649905, 2025). "Recent evidence supports the role of lncRNA H19 as a significant biomarker for the diagnosis and therapeutic intervention of gliomas." (PMID 41149459, 2025). "VEGF signaling is activated and glioma angiogenesis follows when H19, a ceRNA that inhibits miR-138, is upregulated in glioma cells." (PMID 41439968, 2025). "Like TUBA1A, targeting H19 also appears to suppress glioma cell proliferation and enhance sensitivity to chemotherapy, thereby improving clinical outcomes." (PMID 40974979, 2025). "Through RT-qPCR, it was found that lncRNA H19 and Wnt5a are significantly upregulated in glioma tissues and cells, while miR-342 is downregulated." (PMID 38967893, 2024). "We found that H19 is significantly upregulated in GBM when compared with lower-grade gliomas and its expression positively correlates with NG2 expression." (PMID 38318212, 2024). "Further functional analysis confirmed that H19 can directly target miR-342 to promote the expression of Wnt5a and activate the β-catenin signaling pathway to promote angiogenesis in glioma." (PMID 38967893, 2024). "H19 expression in glioma tissues is higher than that in para-carcinoma tissues and is associated with poor prognosis in glioma patients." (PMID 38355574, 2024). "Overexpression of H19 promotes the proliferation and migration of glioma cells, and H19 promotes the proliferation and autophagy of glioma cells through the mTOR/Unc-51-like autophagy-activating kinase 1 (ULK1) pathway." (PMID 38481525, 2024). "H19 is highly expressed in glioma and directly targets miR-342 to upregulate Wnt5a, a target gene of miR-342, to activate the Wnt5a/β-Catenin pathway and suppress tumor apoptosis." (PMID 38355574, 2024). "Since the previous studies have explored the role of the signature genes METTL7B, SSTR2, OXTR, CDKN2C, and H19 in glioma, while TNFRSF11B has been poorly studied, we examined the functional impact of TNFRSF11B on LGG cell behavior." (PMID 37713112, 2024). "Scientists have found that H19 is a potential tumorigenic lncRNA in glioma and have validated its contribution to the autophagy of glioma cells through the PI3K/AKT/mTOR pathway." (PMID 38355574, 2024). "It has been reported that endothelial miR-29a-3p (miR-29a) is sponged by lncRNA H19, which is upregulated in glioma microvessels and ECs cultured in glioma cell-conditioned medium." (PMID 37443725, 2023).